NR6A1 (nuclear receptor subfamily 6 group A member 1)
Description:
Orphan nuclear receptor that binds to a response element containing the sequence 5'-TCAAGGTCA-3'. Acts as a regulator of embryonic stem cell pluripotency by mediating repression of POU5F1/OCT4: binds to the DR0 element within the POU5F1/OCT4 promoter and inhibits POU5F1/OCT4 expression during embryonic stem cell differentiation. Involved in the regulation of gene expression in germ cell development during gametogenesis (By similarity).
Synonyms: GCNF; hGCNF; RTR; hRTR; GCNF1; CT150; NR61
Tractability: Small molecule: it belongs to a druggable protein family.
Target class: Nuclear hormone receptor subfamily 6 group A member 1; Nuclear hormone receptor subfamily 6 group A; Nuclear hormone receptor subfamily 6; Nuclear receptor; Transcription factor
Gene: Protein-coding gene on chromosome 9 (124,517,275 to 124,771,311, reverse strand). Ensembl gene ENSG00000148200.
Subcellular location: Nucleus
Subcellular location (Human Protein Atlas): Nucleoplasm; Centrosome; Cytosol
Pathways (Reactome):
Developmental Biology: POU5F1 (OCT4), SOX2, NANOG activate genes related to proliferation
Gene expression (Transcription): Nuclear Receptor transcription pathway
Gene Ontology:
Molecular function: DNA-binding transcription repressor activity; sequence-specific double-stranded DNA binding; DNA binding; DNA-binding transcription factor activity, RNA polymerase II-specific; estrogen response element binding; nuclear receptor activity; protein homodimerization activity; sequence-specific DNA binding; DNA-binding transcription activator activity, RNA polymerase II-specific; DNA-binding transcription factor activity; RNA polymerase II cis-regulatory region sequence-specific DNA binding; zinc ion binding
Biological process: positive regulation of mesenchymal stem cell differentiation; gamete generation; negative regulation of transcription by RNA polymerase II; regulation of transcription by RNA polymerase II; intracellular receptor signaling pathway; positive regulation of transcription by RNA polymerase II; regulation of DNA-templated transcription
Cellular component: nucleus; chromatin; nucleoplasm; transcription regulator complex
Genetic constraint (gnomAD): Loss-of-function variants: 5 observed, 54.51 expected, observed/expected ratio (o/e) 0.0917, 90% interval 0.047 to 0.19. The upper end of that interval is the gene's LOEUF score, 0.19, which puts it in group 1 of 6, group 1 being the genes least tolerant of losing a copy. Missense variants: 442 observed, 587.79 expected, observed/expected ratio (o/e) 0.75, 90% interval 0.69 to 0.81. Synonymous variants: 239 observed, 228.93 expected, observed/expected ratio (o/e) 1.04, 90% interval 0.94 to 1.16.
Homologues: Orthologues: chimpanzee NR6A1 (99% identical), macaque NR6A1 (99% identical), rabbit NR6A1 (99% identical), dog NR6A1 (99% identical), guinea pig NR6A1 (98% identical), rat Nr6a1 (98% identical), pig NR6A1 (90% identical), mouse Nr6a1 (89% identical), tropical clawed frog nr6a1 (74% identical), zebrafish nr6a1a (71% identical), Drosophila melanogaster Hr4 (31% identical).
Diseases named in the same sentence as NR6A1 in open-access papers:
NR6A1 is named in the same sentence as 34 diseases in open-access papers, as found by Europe PMC text mining. Sharing a sentence is not in itself a finding about the gene and the disease. The quoted sentences say what the papers report.
breast carcinoma (11 papers, 2013 to 2024). "NR6A1 is very lowly expressed in the mammary glands but highly expressed in some types of breast cancer; the ability of NR6A1 to interact with other types of co-repressors such as ERR, N-CoR, and SMRT was demonstrated in various experimental models." (PMID 39624078, 2024). "NR6A1 is normally expressed in germ cells of gonads making it an interesting therapeutic target in breast cancer where unexpectedly it has high expression in both TN and ER + E2197 samples." (PMID 26005638, 2015). "Our data in line with these reports strongly indicate that NR6A1 expression warrants further investigations in breast cancer subtypes, especially in women with TNBC." (PMID 26005638, 2015). "However, recently, it has been reported that NR6A1 is lower expressed in ER+ and ER- breast cancer compared with normal mammary gland tissue, and low levels of NR6A1 in cancer cells exhibit higher sensitivity to the anticancer drug ecteinascidin." (PMID 28969082, 2017). "Mammary-glands contain very low amounts of NR6A1 which are generally up-regulated in breast-cancer." (PMID 26894976, 2016). "Collectively, our data highlight the significant role of the NR6A1/DNMT3A axis suppression in driving the progression of cross-resistance to hormonal and targeted chemotherapies in breast cancer cells." (PMID 39624078, 2024). "We propose that coordinated suppression of NR6A1 and DNMT3A may be critical in sustaining the resistant phenotype and could potentially inform the selection of therapeutic regimens for breast cancer in the future." (PMID 39624078, 2024). "The group of NRs endowed with potential oncogenic properties in breast-cancer is smaller and consists of the Lipid-Sensors, NR1C2 and NR1I2, the Enigmatic-Orphans, NR1F3, NR3B1 and NR5A2, as well as the Orphan-Receptors, NR2E1, NR2E3 and NR6A1." (PMID 26894976, 2016).
prostate carcinoma (11 papers, 2015 to 2026). A carcinoma that arises from epithelial cells of the prostate gland. "And, we found that NR6A1 expression was associated with the cell cycle, the migration and invasion of prostate cancer cells." (PMID 28969082, 2017). "The clinicopathological results indicate that increased NR6A1 expression is associated with advanced prostate cancer." (PMID 28969082, 2017). "Here, we investigated the expression and function of NR6A1 and its underlying mechanisms in prostate cancer (PCa) patients who underwent radical prostatectomy." (PMID 28969082, 2017). "Similarly, expression and correlation analysis reveal that the orphan receptor GCNF (NR6A1) exhibits a notable positive association with both hormone‐sensitive clinical prostate cancer and CRPC." (PMID 40948103, 2026). "NR6A1 gene was associated with migration and invasion in prostate cancer." (PMID 41550951, 2025). "NR6A1 has been reported to promote prostate cancer, gastric cancer, and testicular germ cell tumor progression." (PMID 41219936, 2025). "Studies have shown that the expression level of NR6A1 in cells is closely related to the disease progression of prostate cancer." (PMID 38779358, 2024). "NR6A1 is a nuclear receptor with elevated expression in prostate cancer and is significantly related to tumor cell proliferation and cancer stage." (PMID 33747079, 2021). "NR6A1 protein was found higher in prostate cancer patients compared with those with normal prostate tissue." (PMID 28969082, 2017). "The aim of this study is to indicate that NR6A1 is a positive regulator of prostate cancer progression." (PMID 28969082, 2017). "Knockdown of NR6A1 by small interfering RNA mediated gene silencing and overexpression of NR6A1 through lentivirus were utilized to investigate its potential role in prostate cancer cells." (PMID 28969082, 2017). "To analyze the function of NR6A1 in PCa, we determined NR6A1 protein expression in 303 cases of prostate cancer." (PMID 28969082, 2017). "In contrast, overexpression of NR6A1 reduced G0/G1 phase cell cycle arrest, and promoted metastatic and invasive potential of prostate cancer cells 22RV1." (PMID 28969082, 2017). "A total of 303 cases of prostate cancer after radical prostatectomy were analysed in a tissue microarray (TMA) for NR6A1 immunohistochemistry-based protein expression." (PMID 28969082, 2017). "And silencing expression of NR6A1 in prostate cancer cells by specific siRNA induced cell cycle arrest at the G0/G1 phase, and significantly decreased their invasive and metastatic potentials." (PMID 28969082, 2017). "We further examined the impact of NR6A1 expression on the clinical outcome of prostate cancer patients." (PMID 28969082, 2017). "Expression screening of cancer/testis genes in prostate cancer identified NR6A1 as a novel marker of disease progression and aggressiveness." (PMID 26005638, 2015). "Recently, NR6A1 could serve as a biomarker of disease progression and aggressiveness for prostate cancer (PCa), which showed that increased NR6A1 immunoreactivity was remarkably related to advanced T-stage and cancer cell growth." (PMID 37903971, 2023). "The overexpression of NR6A1 in prostate cancer cells could reduce G0/G1 phase cell cycle arrest and promoted tumor growth." (PMID 34021184, 2021). "In addition, gene silencing of NR6A1 resulted in G0/G1 phase cell cycle arrest, and decreased metastatic and invasive potential of prostate cancer cells DU145 and PC3." (PMID 28969082, 2017). "In addition, NR6A1 levels may be correlated with tumor characteristics in prostate cancer." (PMID 28969082, 2017). "High expression of NR6A1 was observed in prostate cancer cell lines (DU145, PC3, LNCaP, and 22RV1), whereas WPMY-1 showed lower expression of NR6A1." (PMID 28969082, 2017).
prostate carcinoma (continued). "Recent research showed that nuclear receptor subfamily 6, group A, member 1 (NR6A1) regulates lipid metabolism of HepG2 cells, and the positive expression of NR6A1 is a novel marker of disease progression and aggressiveness in prostate cancer patients." (PMID 33274225, 2020). "Interestingly, our findings showed that down regulation of NR6A1 protein expression significantly increased E-cadherin expression, and markedly reduced N-cadherin, Vimentin and ZEB-1 expression in prostate cancer cells (DU145 and PC3), while overexpression of NR6A1 hold the opposite effects." (PMID 28969082, 2017). "In addition, our data also suggested that the siRNA-mediated down-regulation of NR6A1 expression in prostate cancer cells of DU145 and PC3 could reverse the epithelial phenotype and repress a mesenchymal phenotype, and overexpression of NR6A1 in 22RV1 could promote EMT progression." (PMID 28969082, 2017).
hepatocellular carcinoma (4 papers, 2019 to 2025). A malignant tumor that arises from hepatocytes. "After univariate cox regression analysis, lasso analysis and multivariate cox analysis, a five-gene signature (including HDAC1, BIRC5, SPP1, STC2, NR6A1) was constructed to predict the prognosis of hepatocellular carcinoma." (PMID 34616672, 2021). "In addition, NR6A1 was shown to regulate lipid metabolism, insulin-induced proliferation and cell migration in HepG2 hepatocellular carcinoma cells, by acting through AKT/mTORC1 pathway." (PMID 41550951, 2025). "In this study, we identified a novel role NR6A1 in lipogenesis in hepatocellular carcinoma cells." (PMID 31315616, 2019).
coloboma (3 papers, 2024 to 2025). An abnormality in which a part of a structure in one or both eyes is missing. "Expression of NR6A1 is strongly correlated (>5 fold enrichment, p = 0.0024) with that of other coloboma-associated genes in fetal ocular tissues." (PMID 39606382, 2024). "Thus, NR6A1 variants were causative among 1.3% - 1.4% families in two independent patient cohorts (3 out of 224 in the NEI coloboma cohort and 3 out of 215 in the MAC cohort in the UK100KGP)." (PMID 39606382, 2024). "No other candidate pathogenic variants in NR6A1 were identified in the NEI coloboma cohort consisting of a total of 224 probands (66 analyzed by genome sequencing, 57 by exome sequencing, and 101 by amplicon sequencing)." (PMID 39606382, 2024). "We further demonstrated enrichment of coloboma-associated genes with NR6A1 in fetal, but not adult tissues." (PMID 39606382, 2024).
Intellectual disability (3 papers, 2024 to 2025). "As such, phenotypes such as intellectual disability (Individual B1) may be spurious associations or may be uncommon manifestations of an NR6A1-related syndrome." (PMID 39606382, 2024).
microphthalmia (3 papers, 2024 to 2025). Congenital or developmental anomaly in which the eyeballs are abnormally small. "Taken together, these experiments demonstrate that normal zebrafish eye development is sensitive to nr6a1 dosage and both reduced and increased nr6a1 expression result in developmental phenotypes analogous to human colobomatous microphthalmia." (PMID 39606382, 2024). "Here we describe six NR6A1 variants that cause an autosomal dominant syndromic form of colobomatous microphthalmia and missing vertebrae with or without congenital kidney abnormalities, which we term OVR syndrome." (PMID 40610405, 2025). "Here we describe six NR6A1 variants that cause an autosomal dominant syndromic form of colobomatous microphthalmia and missing vertebrae with or without congenital kidney abnormalities, that we term OVR syndrome." (PMID 39606382, 2024). "We identified three rare NR6A1 variants in three families affected by uveal coloboma (COL005, COL034, COL171) with or without microphthalmia, cataract, and missing vertebrae through genome sequencing." (PMID 39606382, 2024).
depression (2 papers, 2022 to 2024). "Furthermore, down-regulation of hippocampal NR6A1 alleviated depression-like behaviors of mice suffering from chronic stress by reversing the decreasing levels of phospho-CREB." (PMID 38372284, 2024). "Hippocampal NR6A1 impairs CREB-BDNF signaling and leads to the development of depression-like behaviors in mice." (PMID 36278681, 2022).
gastric cancer (2 papers, 2021 to 2025). A primary or metastatic malignant neoplasm involving the stomach. "During the development of gastric cancer (GC), the cross-talk between hsa_circ_001653 and NR6A1 was assessed, and the overexpression of NR6A1 restored the proliferation, migration, and invasion of GC cells lacking hsa_circ_001653." (PMID 41219936, 2025).
liver cancer (2 papers, 2023 to 2025). An epithelial or non-epithelial malignant neoplasm that arises from the liver. "In liver cancer, NR6A1 has been reported to be a novel regulator of lipogenesis in HepG2 cells, and NR6A1 knockdown can increase lipid accumulation as well as insulin-induced proliferation and migration of HepG2 cells." (PMID 41219936, 2025).
pancreatic cancer (2 papers, 2025). "Intriguingly, miR-125a-3p, produced from the same pre-miRNA of the -5p, also targets NR6A1 in pancreatic cancer cells, particularly linking NR6A1 to the miRNA, with two out of three predicted sites validated as binding sites for miR-125a-5p in this study." (PMID 39858538, 2025).
testicular germ cell tumor (2 papers, 2020 to 2025). A germ cell tumor arising from the testis. "Previous studies in our laboratory have shown that NR6A1 promotes the progression of testicular germ cell tumors (TGCTs) by targeting E-cadherin." (PMID 41219936, 2025).
breast invasive carcinoma (1 paper, 2024). "Analysis of the breast invasive carcinoma (TCGA-BRCA) dataset showed that methylation of the cg14156446 region is associated with increased NR6A1 expression." (PMID 39624078, 2024).
cervical cancer (1 paper, 2025). A primary or metastatic malignant neoplasm involving the cervix. "Our data revealed that NR6A1 plays an oncogenic role in several types of cancer cells, such as cervical cancer, lung adenocarcinoma and intrahepatic bile duct cancer cells." (PMID 41219936, 2025). "In the present study, we have investigated the function of NR6A1 in several types of cancer cells, including cervical cancer, Cholangiocarcinoma cells, and lung cancer cells, to confirm whether NR6A1 is upregulated in various cancer cells." (PMID 41219936, 2025).
diabetes (1 paper, 2019). "Given its potential role in insulin signaling, we examined the expression of NR6A1 in the livers of diabetes-resistant db/db mice and Goto-Kakizaki (GK) rats." (PMID 31315616, 2019).
endometrial cancer (1 paper, 2021). Primary or metastatic malignant neoplasm involving the endometrium (mucous membrane that lines the endometrial cavity). "The results of Kaplan–Meier prognostic analysis showed that high expression of the risk-associated genes (B3GAT2, CD3EAP, FRMPD3, LINC01224, LINC02068, LY6H, and NR6A1) is related to poor prognosis in endometrial cancer patients (P < 0.05)." (PMID 33747079, 2021).
gastritis (1 paper, 2024). Inflammation of the stomach. "In gastritis, the co-expressed genes NR1I3, NR6A1, and NR0B2 are associated with anti-inflammatory steroid hormone synthesis and metabolism." (PMID 39336801, 2024).
lung adenocarcinoma (1 paper, 2025). A carcinoma that arises from the lung and is characterized by the presence of malignant glandular epithelial cells. "Thus, in the present study, the role and mechanism of NR6A1 in glycolysis were investigated in lung adenocarcinoma, and the clinical association of NR6A1 with lung adenocarcinoma was analyzed." (PMID 41219936, 2025). "We confirmed that high expression of NR6A1 in lung adenocarcinoma tissues was significantly positively correlated with HK1 and p-mTOR expression." (PMID 41219936, 2025). "Taken together, the present research is the first to describe the important regulatory role of NR6A1 in lung adenocarcinoma glycolysis." (PMID 41219936, 2025). "In summary, our data indicate that NR6A1 plays an oncogenic role by reprogramming glycolysis via the miR-302a/HK1 axis in lung adenocarcinoma." (PMID 41219936, 2025). "However, while integrating external database findings with our tissue microarray results (n = 30) has preliminarily revealed the expression profile of NR6A1 in lung adenocarcinoma and its correlation with HK1, the sample size remains constrained." (PMID 41219936, 2025). "Compared with those in the adjacent noncancerous tissue (ANCT) group, high expression of NR6A1 was observed in the lung adenocarcinoma (LUAD) group, whereas the protein levels of HK1 and p-mTOR were high in the LUAD group." (PMID 41219936, 2025).
lung carcinoma (1 paper, 2025). "In view of the similar biological effects of NR6A1 on these three tumor cell lines, we used A549 lung cancer cells as the experimental materials in the following study." (PMID 41219936, 2025). "The relationships between NR6A1 and tumor glycolysis, as well as the regulatory mechanism in lung cancer cells, were subsequently investigated." (PMID 41219936, 2025). "Through a series of experiments, including bioinformatics analysis, dual-luciferase reporter gene expression, RT‒qPCR and Western blot analysis, we proved that NR6A1 could inhibit miR-302a in lung cancer cells, thereby indirectly promoting the expression of HK1." (PMID 41219936, 2025). "We wondered whether NR6A1 downregulates miR-302a in lung cancer cells." (PMID 41219936, 2025). "Taken together, the results of rescue experiments revealed that NR6A1 promotes glucose metabolism and proliferation through miR-302a/HK1 in lung cancer cells." (PMID 41219936, 2025).
melanoma (1 paper, 2025). A malignant, usually aggressive tumor composed of atypical, neoplastic melanocytes. "GNAI1, ADCY1 and NR6A1 common target genes involved in the restriction of cAMP signal transduction and of the activation of mTOR pathway signaling were identified among the target genes in the lipid metabolism pathways dysregulated in resistant melanoma cells." (PMID 41550951, 2025). "Notably, the inhibition of the miRNAs in the resistant cell lines increased the expression of GNAI1 and NR6A1 and reduced melanoma cell growth." (PMID 41550951, 2025).